TPTE2P3 (TPTE2 pseudogene 3)
Gene: Transcribed unprocessed pseudogene on chromosome 13 (52,503,320 to 52,586,906, forward strand). Ensembl gene ENSG00000244471.
Diseases named in the same sentence as TPTE2P3 in open-access papers:
TPTE2P3 is named in the same sentence as 2 diseases in open-access papers, as found by Europe PMC text mining. Sharing a sentence is not in itself a finding about the gene and the disease.
TPTE2P3 shares sentences with these, for which no sentence is quoted: anxiety disorder (2 papers); Anxiety (1).